STAG2 (STAG2 cohesin complex component)
Diseases named in the same sentence as STAG2 in open-access papers (continued):
Sharing a sentence is not in itself a finding about the gene and the disease.
STAG2 also shares sentences with these, for which no sentence is quoted: endometrial cancer (3 papers); influenza (3); acute leukemia (2); epilepsy (2); microcephaly (2); acute lymphoblastic leukemia (1); adenocarcinoma (1); Ataxia (1); bipolar disorder (1); Cannabis use (1); colon adenocarcinoma (1); depression (1); dilated cardiomyopathy (1); Down syndrome (1); ependymoma (1); gastric cancer (1); glaucoma (1); hematological neoplasms (1); hepatoma (1); HIV-1 infection (1); Hutchinson-Gilford progeria syndrome (1); hydatidiform mole (1); ischaemic heart disease (1); kidney cancer (1); lymphopenia (1); medulloblastoma (1); meningioma (1); myelofibrosis (1); myeloma (1); Neurodevelopmental delay (1).
A further 9 diseases each share a sentence with STAG2 in 1 paper.